MCM7 (minichromosome maintenance complex component 7)
Diseases named in the same sentence as MCM7 in open-access papers (continued):
Sharing a sentence is not in itself a finding about the gene and the disease.
triple-negative breast carcinoma (1 paper, 2018). An invasive breast carcinoma which is negative for expression of estrogen receptor (ER), progesterone receptor (PR), and human epidermal growth factor receptor 2 (HER2). "MCM2 to MCM7 may regulate the synergistic activation of apoptosis in triple negative breast cancer." (PMID 29867845, 2018).
uterine fibroids (1 paper, 2021). "Reducing the expression of ER in women who gave birth may thus reduce, among others, the expression of MCM-7 and thus explain the protective effect of past pregnancies and deliveries on the occurrence of uterine fibroids." (PMID 34449552, 2021).
tumor (103 papers, 2007 to 2025). "Among them, MCM7 is implicated in tumor development and progression, and is considered as a potential biomarker for a variety of human malignancies." (PMID 37696392, 2024). "The MCM7 protein is associated with tumor cell proliferation that plays an important role in different human cancer progression." (PMID 35087187, 2022). "MCM proteins including MCM7 have been utilized as diagnostic and prognostic tumor markers for their higher specificity and sensitivity than the conventional proliferative markers, such as Ki-67 and PCNA." (PMID 32596300, 2020). "Our results showed that mRNA levels of MCM2, MCM6 and MCM7 were associated with certain features of tumor and the outcomes of HCC patients." (PMID 29463213, 2018). "Correlation analysis showed that MCM6 protein levels were significantly associated with Ki67 expression and differentiation, MCM7 with tumor size and Ki67 (P < 0.05)." (PMID 29463213, 2018). "To verify the inhibition of tumor growth in vivo was caused by MCM7 knockdown, we further detected the expression of MCM7 and cyclin D1 in those xenograft tumors." (PMID 28182015, 2017). "Ki-67 and MCM7 LIs were both significantly associated with increasing tumor size, mitotic rate and risk." (PMID 28983330, 2015). "Significant associations were noted between MCM7 and Ki-67 LIs and tumor size (P = 0.001 and 0.003 respectively), mitotic rate (P < 0.001 both) and risk stratification (P < 0.001 both)." (PMID 28983330, 2015). "Despite the established clinicopathological value of Ki-67 in GISTs, detection of MCM7 expression is recommended as a prognostic adjunct, given its better sensitivity for cellular proliferation and stepwise association with tumor risk." (PMID 28983330, 2015). "Significant associations were found between MCM7 and Ki-67 LIs and tumor size (P = 0.001 and 0.003 respectively), mitotic rate (P < 0.001 both) and risk stratification (P < 0.001 both) with a stepwise increase in MCM7 LIs with increasing tumor risk." (PMID 28983330, 2015). "High expression of the MCM7 protein in tumour cells (index ⩾140) was associated with better CSS (P=0.005)." (PMID 22333708, 2012). "Consequently, MCM7 has been described as a tumor-associated gene and is considered a biomarker or even a therapeutic target." (PMID 40943553, 2025). "BVP reduced Mcm7 expression and authors claimed that this was associated with DNA damage in prostate cancer cells and tumor tissues, although detailed mechanism still remains unclear." (PMID 29651420, 2018). "Elevated MCM2, MCM6 and MCM7 were associated with adverse tumor features and poorer outcomes." (PMID 29463213, 2018). "Furthermore, a positive association between MCM7 and cyclin D1 expression was found in mouse model and human tumor tissues." (PMID 28182015, 2017). "Higher MCM7 expression was found to be associated with more aggressive malignant characteristics, such as poorer tumor differentiation (P=0.001), higher frequency of vein invasion (P=0.015) and more advanced tumor stage (TNM staging: P<0.001 and BCLC staging: P=0.026)." (PMID 28182015, 2017). "In addition, a stepwise increase in MCM7 LIs in relation to tumor risk was more frequently seen than in Ki-67." (PMID 28983330, 2015). "Targeting MCM7 by statins has recently been shown to have an inhibitory effect on the proliferation of tumor cells." (PMID 38182577, 2024). "Inhibition of MCM7 expression using simvastatin resulted in reduced proliferation and tumor cell growth of double-knockout young BM cells." (PMID 38182577, 2024). "MCM2 and MCM7, defined as CRC-related genes, were overexpressed and associated with proliferative capacity, tumor histological grade, lymph node metastasis and vascular invasion in CRC." (PMID 39520627, 2024). "Meanwhile, MCM7 is widely regarded as an extensive biomarker in multiple tumor types since its overexpression pattern." (PMID 36776764, 2023). "MCM7 has been found to be involved in the immune response of the spleen, thereby influencing tumor development." (PMID 37531195, 2023).
tumor (continued). "MCM7 has been suggested as an unfavorable factor in other tumor types and significantly correlated with Ki67 expression." (PMID 35892846, 2022). "As an important license factor in DNA replication initiation, plenty of studies have verified the crucial role of MCM7 in tumor proliferation, cancer stemness, migration and invasion." (PMID 35040374, 2022). "Additional members of the MCM complex (i.e. MCM2, MCM3, MCM6, and MCM7) were upregulated in all sample groups but basal-like TN tumours." (PMID 36220861, 2022). "Several mature miRNAs of the mir‐106b~mir‐93~mir‐25 cluster were also significantly overexpressed in tumours with 3′ fusions of the host gene MCM7." (PMID 35182081, 2022). "Next, we examined MCM7 expression in tumor tissues and adjacent normal tissues from 50 ccRCC patients." (PMID 34993142, 2021). "Tumor progression-free survival and multivariate analysis identified the MCM7-geminin status as an independent prognostic factor in laryngeal SCC rather than MCM7 and geminin covariates separately." (PMID 32089988, 2020). "Metastatic lesions of CLP mice had a consistently higher labeling index of MCM7 than that of sham-treated mice (57.1 ± 11.2% vs. 25.5 ± 9.2%), indicating that an intra-abdominal infection caused by CLP enhanced tumor cell proliferation in the metastatic sites." (PMID 32630328, 2020). "As we expected, MCM7 knockdown inhibits the tumor-initiating ability, and MCM7 ectopic expression abolishes the inhibitory effects of ATO." (PMID 31186405, 2019). "We found that HCC patients with elevated expression of MCM7 in tumor tissues are likely to have poor prognosis." (PMID 31186405, 2019). "The elevated expression of MCM7 was highly correlated with the tumor diameter, Edmondson–Steiner grading, survival time, portal venous emboli, and AFP concentration of HCC patients." (PMID 31186405, 2019). "The labeling index (LI) of Mcm7 in immunohistochemistry was more reliable than that of Ki-67 in several types of cancer and is strongly correlated to the tumor aggressiveness in astrocytoma and oral squamous cell carcinoma." (PMID 29651420, 2018). "MCM2, MCM6 and MCM7 proteins were expressed at significantly higher levels in HCC compared to non-tumor specimens (P < 0.01), and the degree of their immunoreactivity gradually increased from normal and cirrhotic livers to HCC." (PMID 29463213, 2018). "Consistently, we also observed that IHC index of MCM7 in HCC tumor was significantly higher than that in paired normal liver tissue." (PMID 28182015, 2017). "Immunohistochemical analysis of 150 NSCLC patient samples revealed that both lamin B2 and MCM7 levels positively correlated with histological grade and tumor TNM stage." (PMID 29285216, 2017). "mRNA and protein levels of both RACK1 and MCM7 were higher in tumor tissue than in the normal lung counterparts." (PMID 28465488, 2017). "Fourteen of our 1552 tumor samples (0.9%) had MCM7 3ʹ fusion transcripts including mir-106b/93/25 and a single sample had a 5ʹ fusion." (PMID 28983113, 2017).
tumor (continued). "We found a significant positive correlation between MCM7 and cyclin D1 expression in HCC tumor tissues that confirmed the involvement of MCM7–cyclin D1 pathway in HCC." (PMID 28182015, 2017). "Markedly, cancer cells often express DNA replication factors including the MCM helicase at high levels, and MCM2 and MCM7 are considered as biomarkers and potential therapeutic targets for cervical, colorectal and other tumours (for example, refs 50, 51, 52)." (PMID 26876972, 2016). "Because of this role, the MCM protein family (MCM2 to MCM7) consists of important histological markers to determine cell replication and thus, together with Ki-67, determines prognostic factors in various neoplasms." (PMID 26823641, 2015). "Meanwhile, positive immunohistochemical staining of Mcm7 and Ki67 was observed in the nucleus of the tumor cells." (PMID 25202351, 2014). "MCM7 overexpression and amplification occurs in several human malignancies, although MCM7 takes part in both oncogenic and tumor suppressor signaling pathways." (PMID 24392146, 2014). "MCM7 shows significant difference between tumor (0.674±0.396, median = 0.72, p = 0.035) and normal (0.574±0.844, median = 0.35), but cell lines (0.65±0.245, median = 0.715) do not show significant difference." (PMID 23874974, 2013). "Unsupervised hierarchical cluster based on relative quantification of the 5 E2F-induced genes, CCNA2, CCNB1, CCNB2, MSH6 and MCM7, by RT–qPCR divided the 24 tumours into two groups." (PMID 22045185, 2011). "This study investigates whether miRNAs from the miR-106b-25 cluster regulate common target genes, enhance one another’s effect, and act synergistically with MCM7 to promote tumor progression." (PMID 40943553, 2025). "We observed upregulated MCM7 transcript and protein levels in tumor samples compared to controls." (PMID 40943553, 2025). "Notably, all DNA helicase MCM subtypes, typically upregulated in tumours including GBM, were consistently downregulated during differentiation, with MCM7 deficiency known to inhibit GBM proliferation." (PMID 40070092, 2025). "In addition, SVA treatment in vivo resulted in a reduction in tumor size and weight, which was accompanied by a decrease in MCM7 protein levels." (PMID 38182577, 2024). "Inhibition of MCM7, a known Myc target, attenuates OS tumor formation." (PMID 38182577, 2024). "Oxaliplatin or etoposide‐mediated chemotherapy combined with knockdown of MCM7 could reduce the proliferation of colorectal carcinoma cells and induce tumor apoptosis in vitro." (PMID 36776764, 2023). "Silencing MCM7 significantly inhibited tumor cell proliferation and could serve as a prognostic marker of NSCLC." (PMID 38077434, 2023). "More specifically, several studies reported that increased expression of S100A6 promoted cell proliferation by regulating the expression of IL‐8, CDK5, CDK4, MCM7, Bcl2, and could be used as a marker of tumor aggressiveness in gastric cancers." (PMID 34857857, 2021). "In particular, cell cycle genes such as CSNK2A1, MCM8, CDK19, KIFC1 and MCM7, among which KIFC1 was previously found to be a factor for poor prognostic and a therapeutic target associated with tumour proliferation in HCC34,35, even though its immunodulatory function has never been described before." (PMID 33431814, 2021). "Induced overexpression of MCM7 is involved in tumor formation and progression in a variety of human malignancies, including PC, and its down-regulation results in growth inhibition, indicating that MCM7 is particularly important as a potential biomarker." (PMID 34573332, 2021). "A previous study showed that high MCM7 expression was associated with male gender, non-adenocarcinoma histology and poor tumor differentiation in NSCLC patients." (PMID 33936158, 2021). "Furthermore, we used psicoR-scramble/shMCM7 transfected Huh7.5.1 cells and HCCLM3 cells, the two cell lines with the most significant downregulation of MCM7 protein, to examine the tumor-initiating capacity of these HCC cells." (PMID 31186405, 2019).
tumor (continued). "Conditional expression of Mcm7 in mice was shown to induce tumor formation." (PMID 29651420, 2018). "Moreover, both RACK1 and MCM7 levels were positively correlated with histological grade, lymphatic metastasis, and tumor TNM stage." (PMID 28465488, 2017). "Moreover, a combination of the whole miR-106b~25 cluster expression and MCM7 LI distinguished tumor invasiveness even better, as evidenced by AUC = 0.9133 (95% CI 0.8054–1.000)." (PMID 28432562, 2017). "Interestingly, the death risk of low MCM7 expression on OS was found to be smaller in those HCC patients with less malignant characteristics, such as low AFP level (< 200 ng/ml), small tumor size, single tumor number and early BCLC stage (all P⩽0.036)." (PMID 28182015, 2017). "A combination of MCM7 LI and miR-106b~25 cluster expression was able to accurately differentiate invasive from noninvasive tumors and had a significant discriminatory ability to predict postoperative tumor recurrence/progression." (PMID 28432562, 2017). "Furthermore, we performed Annexin V-FITC/PI flow cytometry to assess the effect of MCM7 downregulation on tumor cell apoptosis." (PMID 28182015, 2017). "The mechanistic investigations revealed that knockdown of MCM7 resulted in the cell cycle arrest of HCC cells with the subsequent inhibition of tumor growth, suggesting that MCM7 might be a potential target for cancer therapy." (PMID 28182015, 2017). "In one tumor MCM7 had fusions with two different 5ʹ partner genes both leading to upregulation." (PMID 28983113, 2017). "Cell proliferation markers (Ki-67, MCM-7) were expressed in <5% of the tumor cells." (PMID 28390134, 2017). "MCM7 and Ki-67 immunoreactivity was noted in the nuclei of the tumor cells." (PMID 28983330, 2015). "Evaluation of MCM7 expression in GISTs may provide a more objective assessment of cellular proliferation and better prediction of tumor aggressiveness." (PMID 28983330, 2015). "Abnormal Mcm7 expression is observed in numerous tumor types and correlates with a poor prognosis." (PMID 25202351, 2014). "Furthermore, we report that MCM7 is strongly correlated with patient outcome in patients with WHO grade II-IV tumor." (PMID 25046975, 2014). "The discrepancy of correlation of MCM2, MCM5 and MCM7 may be due to a very small sample size in tumor stage I (N = 06)." (PMID 23874974, 2013). "The average fold change of MCM7 in tumor is 1.15(±0.68) and in cell lines 1.11(±0.414)." (PMID 23874974, 2013). "microRNA93 (mir-93), a member of the mir106b-25 cluster, located in intron 13 of the MCM7 gene, although frequently overexpressed in human malignancies may also function as a tumor suppressor gene." (PMID 22685420, 2012). "Cyclin-dependent kinase inhibitor 2A (p16) and MCM7 were significantly upregulated in one of the tumour subsets, indicating that this subset (Gr2) could be characterised by E2F-regulated transcription." (PMID 18349847, 2008). "Thus, we may hypothesize that the MCM7 gene may be a candidate marker involved in the development of various types of neoplasms." (PMID 31936215, 2020). "Given the critical role of MCM7 in DNA replication licensing and causing chromosome instability, and the strong association between MCM7 and cyclin D1 expression in both human HCC tissue and murine xenograft tumor, it is reasonable to hypothesize that MCM7 acts as a regulator of cyclin D1." (PMID 28182015, 2017). "Moreover, both lamin B2 and MCM7 levels correlated with histological grade, and tumor TNM stage." (PMID 29285216, 2017). "Furthermore, the expression of miR-106b~25 alone (AUC = 0.830; 95% CI 0.6652–0.9941) and in combination with MCM7 (AUC = 0.821; 95% CI 0.6477–0.9933) discriminated patients with post-surgery residual tumor from those that underwent successful radical operation." (PMID 28432562, 2017).